FPR1 (formyl peptide receptor 1)
Description:
Pattern recognition G protein-coupled receptor (PRR/GPCR) involved in innate recognition of N-formyl-methionyl peptides derived from invading microbes and host mitochondria as pathogen- and damage-associated molecular patterns (PAMPs and DAMPs). Functions as a sensor of PAMPs and DAMPs released upon microbial infection or tissue damage, triggering immune cell activation and chemotaxis to eliminate pathogens and restore tissue homeostasis. Peptide binding leads to conformational changes coupled to heterotrimeric G(i) protein signaling. Upon GDP to GTP conversion, G(i)-alpha subunit dissociates from G-beta and G-gamma subunits. Free G(i)-alpha subunit inhibits cyclic adenylate cyclase and cAMP synthesis whereas the G-beta and G-gamma dimer activates downstream phospholipase C-beta and phosphoinositide 3-kinase signaling cascades leading to Ca(2+) influx. Displays two affinity states for peptide agonists, low and high, likely accounting for selective signaling of myeloid cell functions at different phases of the inflammatory response. Subnanomolar concentrations of peptide agonists induce myeloid cell chemotaxis, whereas micromolar concentrations trigger degranulation and superoxide production. May recognize a myriad of bacterial signal peptides indicative of an evolutionary conserved detection mechanism in host defense against bacterial infection. Triggers bactericidal functions of neutrophils and phagocytes in response to N-formyl-Met-Leu-Phe (fMLF) which is part of the signal peptide sequences of hundreds distinct bacterial strains. In the homeostatic wound healing response to tissue injury, senses 'necrotaxis' DAMP-type signals released in the form of mitochondria-derived N-formylated peptides and guides neutrophil trafficking toward necrotic cells within the injury site (By similarity). In the context of antitumor immunity, interacts with ANXA1 and guides dendritic cell positioning in close proximity to necrotic tumor cells, allowing for tumor-associated antigen uptake and cross-presentation to T cells. Receptor for TAFA4, mediates its effects on chemoattracting macrophages, promoting phagocytosis and increasing reactive oxygen species (ROS) release. Receptor for cathepsin CTSG, leading to increased phagocyte chemotaxis. Beyond canonical N-terminal formylated peptide agonists, can also be activated by C-terminal amidated peptides, which appear to all share a tripartite structure motif oriented around a carboxyl group. Differential signaling is also defined by receptor oligomerization state. Pro-resolving ligands, such as lipoxin A4 or ANXA1, induce the formation of FPR1:FPR2 heterodimers triggering proapoptotic JNK pathway in neutrophils. (Microbial infection) Used by Y. pestis as a receptor on human immune cells. Upon infection, Y. pestis releases N-formyl peptides that activate FPR1-mediated immune signaling and chemotaxis. This leads to Y. pestis docking on FPR1 via the lcrV needle cap protein of its type III secretion system (T3SS) followed by the delivery of effector proteins into host immune cells, ultimately triggering immune cell apoptosis.
Synonyms: FPR; FMLP
Tractability: Small molecule: a structure with a bound ligand is known; a high-quality ligand is known; it belongs to a druggable protein family. Antibody: UniProt places it where antibodies can reach, with high confidence; its Gene Ontology location is reachable by antibodies, with high confidence; UniProt predicts a signal peptide or a membrane-spanning region. PROTAC: its protein half-life has been measured; a small molecule that binds it is known.
Target class: N-formyl methionyl peptide receptor; Peptide receptor (family A GPCR); Membrane receptor; Family A G protein-coupled receptor
Chemical probes: ML048, N-Formyl-Met-Leu-Phe (high quality)
Gene: Protein-coding gene on chromosome 19 (51,745,172 to 51,804,115, reverse strand). Ensembl gene ENSG00000171051.
Subcellular location: Cell membrane
Subcellular location (Human Protein Atlas): Golgi apparatus; Nucleoli; Nucleoplasm
Pathways (Reactome):
Immune System: Interleukin-10 signaling; Neutrophil degranulation
Signal Transduction: Formyl peptide receptors bind formyl peptides and many other ligands; G alpha (i) signalling events
Gene Ontology:
Molecular function: G protein-coupled receptor activity; G protein-coupled receptor binding; N-formyl peptide receptor activity; protein binding; complement receptor activity; RAGE receptor binding; scavenger receptor binding
Biological process: phospholipase C-activating G protein-coupled receptor signaling pathway; adenylate cyclase-modulating G protein-coupled receptor signaling pathway; chemotaxis; complement receptor mediated signaling pathway; G protein-coupled receptor signaling pathway; inflammatory response; positive regulation of cytosolic calcium ion concentration; signal transduction
Cellular component: plasma membrane; azurophil granule membrane; cytoplasm; ficolin-1-rich granule membrane; membrane; secretory granule membrane
Genetic constraint (gnomAD): Loss-of-function variants: 1 observed, 0.61 expected, observed/expected ratio (o/e) 1.64, 90% interval 0.32 to 1.92. That is too few expected variants to judge how well the gene tolerates losing a copy. Missense variants: 407 observed, 476.51 expected, observed/expected ratio (o/e) 0.85, 90% interval 0.79 to 0.93. Synonymous variants: 193 observed, 186.6 expected, observed/expected ratio (o/e) 1.03, 90% interval 0.92 to 1.16.
Homologues: Orthologues: chimpanzee FPR1 (99% identical), macaque FPR1 (89% identical), rabbit FPR1 (79% identical), mouse Fpr1 (76% identical), rat Fpr1 (72% identical). Paralogues in human: FPR2 (69% identical), FPR3 (59% identical), CMKLR1 (34% identical), C3AR1 (33% identical), GPR32 (32% identical), C5AR1 (29% identical), GPR33 (27% identical), C5AR2 (26% identical).
Diseases named in the same sentence as FPR1 in open-access papers:
FPR1 is named in the same sentence as 202 diseases in open-access papers, as found by Europe PMC text mining. Sharing a sentence is not in itself a finding about the gene and the disease. The quoted sentences say what the papers report.
glioblastoma (23 papers, 2010 to 2025). The most malignant astrocytic tumor (WHO grade IV). "For instance, FPR2 may promote the malignancy of human colon cancer, while FPR1 is linked to the progression of human glioblastoma multiforme (GBM)." (PMID 32038501, 2020). "FPR1 activation promotes multiple cellular processes, such as chemotaxis, proliferation, and angiogenesis, in glioblastoma multiform." (PMID 41283264, 2025). "Huang’s and Zhou’s groups showed that AnxA1 or other ligands released by glioblastoma multiforme necrotic cells would mediate FPR1 activation." (PMID 34571894, 2021). "In glioblastoma multiforme cells, several studies demonstrated that FPR1 activation mediates tumor cells’ chemotaxis, invasion, proliferation and angiogenesis." (PMID 34571894, 2021). "Walenkamp has previously shown that expression of FPR1 in human glioblastoma cells depends on the tumour microenvironment." (PMID 33057069, 2020). "FPR1 is known to play a role in tumourigenicity of other cancers including glioblastoma and hepatocellular carcinoma." (PMID 31170199, 2019). "Both formylated peptides and Annexin A1 released from necrotic glioblastoma cells have been demonstrated to promote tumor growth via activation of FPR1." (PMID 31170199, 2019). "Highly malignant human glioblastomas have been reported to selectively overexpress FPR1, with activation promoting cancer progression and metastasis." (PMID 31170199, 2019). "Taken together, these data suggest that FPR1 play an important role in tumor invasion in colorectal cancer, gastric cancer, and glioblastoma." (PMID 28724995, 2017). "Our data are in line with results reported in a human glioblastoma model, in which FPR1 expressing U-87 cells that were either silenced by siRNA or inhibited by FPR1 antagonist exhibited a delayed tumorigenicity in vitro." (PMID 27432059, 2016). "This could explain why FPR1, in other cancer contexts, exerts different functions: in the context of human glioblastoma, FPR1 confers a more invasive and angiogenic phenotype and modulates the tumor microenvironment to favor immunosuppression." (PMID 41425092, 2025). "We next tested whether the peptide f-MVPIKI and its derivatives could induce intracellular Ca2+ release in the human glioblastoma cell line U87-MG that is known to express FPR1, FPR3 and trace amounts of FPR239 (Supplement 2)." (PMID 40940450, 2025). "Moreover, the tumorigenicity of the glioblastoma cells was significantly reduced in AnxA1 knockout mice, while FPR1/AnxA1 double gene knockout mice were more effective in inhibiting tumor growth than AnxA1 knockout mice." (PMID 34650406, 2021). "However, the expression and the relevance of FPR1 in glioblastoma is established in multiple sources." (PMID 33057069, 2020). "Expression of FPR1 was detected in the following human cancer cell lines: U87-MG (glioblastoma), PC-3, DU-145, LnCap (prostate), SH-SY-5Y (neuroblastoma), K-562 (chronic myelogenous leukaemia), HCT-116, SW620, SW480 and HT-29 (colorectal), A549 (lung) and MDA-MB-231 (breast)." (PMID 33057069, 2020). "However, since chondrosarcoma cells have been reported to secrete VEGF and glioblastoma cells bearing FPR1 produce VEGF in response to fMLF, it will be interesting to investigate the possibility that [SRSRY] exerts such effect on VEGF-triggered angiogenesis." (PMID 27323409, 2016). "Furthermore, it has been shown that inhibition of FPR1-triggered ERK1/2 phosphorylation reduces nuclear translocation of HIF-1α in glioblastoma cells." (PMID 27323409, 2016). "Formyl peptide receptor 1 (FPR1) activity in U87 glioblastoma (GBM) cells contributes to tumor cell motility." (PMID 25894595, 2015). "In this respect, ligands released by necrotic glioblastoma cells, along with ANXA1, can mediate FPR1 activation." (PMID 41283264, 2025). "We chose to study the efficacy of FPR1 antagonist ICT12035 in vitro and in vivo in the glioblastoma cell line, U87-MG." (PMID 33057069, 2020).
glioblastoma (continued). "Previous studies have shown that tumour cells from highly malignant human glioma specimens express FPR-1; subsequently it has been shown that ANXA1 released by necrotic human glioblastoma cells was able to stimulate tumour cell growth through FPR-1." (PMID 25510623, 2014). "FPR1, in malignant glioblastoma multiforme (GBM) cells, is activated by the endogenous chemotactic ligand annexin 1 (ANXA1) released by necrotic GBM cells and functionally interacts with the EGFR to promote survival and invasiveness of GBM cells." (PMID 33923400, 2021).
Sepsis (22 papers, 2008 to 2025). Sepsis is defined as life-threatening organ dysfunction caused by a dysregulated host response to infection. "In the context of sepsis, dysregulated FPR1 expression leads to impaired immune cell recruitment and function; consequently, FPR1 has been suggested as a putative target for several diseases, including sepsis." (PMID 40861493, 2025). "For instance, EVs released from probiotic bacteria can enhance macrophage phagocytosis in polymicrobial sepsis through activation of the FPR1/2 pathway." (PMID 39967672, 2025). "Second, there are many ligands of FPR1, including the HSP, lipoxin A4, cathepsin G and so on, we only detected the concentration of MT-ND6 and ANXA1 in this study, which was insufficient to revel the comprehensive functions of FPR1 in sepsis." (PMID 39611143, 2024). "So, large-sample, multi-center, and multi-time point clinical studies are needed to further explore the roles of FPR1 and its ligands in sepsis." (PMID 39611143, 2024). "Our findings provide valuable models testing patient risk prediction and strengthen the evidence for agonists of FPR1, MT-ND6 and ANXA1, as novel biomarker for patient selection for novel therapeutic agents to target mtDAMPs and regulator of GPCRs in sepsis." (PMID 39611143, 2024). "FPR1 is predominantly expressed in neutrophils and rapidly upregulated in response to various inflammatory stimuli, including sepsis and autoimmune diseases." (PMID 33796096, 2021). "To assess the potential therapeutic strategy of NFP degradation in SIRS and sepsis, we still need to understand the settings in which activation or inhibition of FPR-1 is beneficial or detrimental to injury repair and pathogenic clearance." (PMID 31244835, 2019). "The top ten differentially expressed genes in this study include Gm29879, Lcn2, Cxcl10, Zbp1, Lbhd2, C5aR1, Cxcl10, Lbhd2, Cxcl9, and Fpr1, all of which might play a role in the pathophysiology of sepsis-induced WMI." (PMID 41584453, 2025). "This study demonstrates that LGG-derived BEVs may have therapeutic effects against sepsis-induced organ injury and mortality through enhancing FPR1/2-mediated macrophage phagocytosis." (PMID 39543493, 2024). "Our group has investigated the links between trauma, vascular collapse and sepsis, and our results suggest that NFPs and FPR-1 may serve as that link." (PMID 31244835, 2019). "ANXA1 and FPR1 play a crucial role in the occurrence of adrenal insufficiency by regulating cholesterol ester storage and may represent a novel therapeutic target for maintaining adrenal cortex hormone synthesis in sepsis patients." (PMID 40426888, 2025). "Another notable pathway expressed at higher levels in sepsis survivors related to the receptor for advanced glycation endproducts (RAGE) pathway and included the RAGE-related genes S100A8, S100A9, S100A12, and formyl peptide receptor 1 (FPR1)." (PMID 25538794, 2014). "FPR1, a chemoattractant GPCR predominantly expressed in neutrophils, macrophages, and monocytes, plays a critical role in immune modulation and inflammation, positioning it as a compelling therapeutic target in sepsis." (PMID 40761792, 2025). "FPR-1-NFP interaction may serve as the missing link between host-derived danger signals, inflammation and vascular dysfunction in SIRS and sepsis." (PMID 31244835, 2019). "Peptide deformylase, a metalloenzyme, has the inherent activity to degrade NFPs before they bind FPR-1, and may in fact serve as a potential pharmacologic agent for the treatment of trauma-induced SIRS and sepsis." (PMID 31244835, 2019). "In summary, our study demonstrates that exogenous CO inhibits sepsis-induced neutrophil infiltration by interfering with FPR1 via p38 MAPK but not GRK2." (PMID 27144520, 2016). "However, the unaltered expression of FPR1 is critical for the perseverance of the functional response to fMLP, compared with the decreased expression of CXCR1 and CXCR2 and the impaired response to its ligand, IL-8, in murine sepsis." (PMID 27144520, 2016).
Sepsis (continued). "Both FPR1 and CXCR2 have been shown to be downregulated by induction of GRK2 in sepsis." (PMID 24755316, 2014). "Formyl peptide receptor 1 (FPR1) is a member of G protein-coupled receptor (GPCR) family that detects potentially danger signals characterized by the appearance of N-formylated peptides which originate from either bacteria or host mitochondria during organ injury, including sepsis." (PMID 39611143, 2024). "Bacterial and mitochondrial NFPs, and their activation of FPR-1 in immune and non-immune cells, may serve as a link to the underlying pathophysiology of trauma-induced SIRS and sepsis." (PMID 31244835, 2019).
COVID-19 (20 papers, 2020 to 2025). A disease caused by infection with severe acute respiratory syndrome coronavirus 2. "Because plasma-mediated neutrophil activation through fMet/FPR1 signalling was observed in COVID-19 patients, we next assessed the association of neutrophil activation marker calprotectin with fMet levels." (PMID 37248708, 2023). "In the lungs of COVID-19 patients, AnxA1/FPR1 pair interaction was shown to be enhanced during infection and crucial for the interplay between squamous epithelial cells and myeloid cells, such as neutrophils and macrophages." (PMID 40956847, 2025). "FPR1 was found to induce blood neutrophil activation in COVID-19 patients, triggering neutrophil-mediated inflammation and end-organ damage." (PMID 38674681, 2024). "We performed a study using peripheral blood mRNA-seq data from 41 COVID-19 patients to obtain the immune-characterized genes of COVID-19 severe disease, namely, the hub genes (FPR1, FCGR2A, TLR4, S100A12, CXCL1, and LTF)." (PMID 38674681, 2024). "Plasma-mediated neutrophil activation through fMet/FPR1-dependent mechanism was evident, suggesting that fMet plays a central role in neutrophil activation and contributes to the pathogenesis of COVID-19." (PMID 37248708, 2023). "These cell adhesion molecules (ANXA1 and ICMA2), cytokine binding and receptor activity genes (CD44, CD45, CD47, CD74, and THBS1), and inflammatory genes (FPR1 and SELL) have been reported to be associated with COVID-19." (PMID 35172892, 2022). "We investigated whether elevated levels of fMet present in COVID-19 patient plasma could promote neutrophil activation through FPR1." (PMID 37248708, 2023). "In summary, our data highlight the clinical value of measuring neutrophil-derived activation markers in COVID-19, and more importantly, identifying a novel potential therapeutic target, FPR1, to regulate neutrophil-mediated inflammation and end-organ damage in COVID-19." (PMID 37248708, 2023). "In the combined mild and moderate/severe symptoms group of COVID-19 patients, levels of calprotectin correlated significantly with fMet levels (r = 0.60, p = 0.0007), an observation consistent with fMet/FPR1-mediated neutrophil activation from this subgroup of COVID-19 patients." (PMID 37248708, 2023). "Previous studies on COVID-19 have suggested that FPR1 and MAPK3 may be potential therapeutic drug targets." (PMID 36052061, 2022). "Among them, SLC2A3 and FPR1 demonstrated high expression in the severe COVID-19 in PBMC samples." (PMID 34239034, 2021). "CCR1 and FPR1 were highly expressed in macrophages enriched in the severe COVID-19 group." (PMID 34239034, 2021). "And the subsequent PPI analysis results in our study also confirmed that chemokines related to inflammatory responses, such as CCR1, CCL19, and CXCL10, and the immune response-related gene FPR1 presented significant expression changes in the progression of COVID-19." (PMID 33195212, 2020). "Interestingly, many pro-inflammatory genes including S100A8 and S100A9, chemotaxis genes such as CXCR2 and FPR1, and NETosis-associated genes such as TIMP1 were highly expressed in neutrophils of ANPEP-high patients with COVID-19 compared with ANPEP-low patients with COVID-19." (PMID 40168094, 2025). "Thus, mitochondrial-derived fMet may be a crucial factor contributing to neutrophil-mediated inflammation in COVID-19 in an FPR1-dependent manner." (PMID 37248708, 2023). "Based on the Degree, MCC, Closeness, Betweenness, and MNC algorithms of the CytoHubba plug-in, six genes (FPR1, FCGR2A, TLR4, S100A12, CXCL1, and LTF) were confirmed as hub genes related to COVID-19 severe." (PMID 38674681, 2024). "Particularly, many inflammation genes, such as C5AR1, CD55, CSF3R, CXCL8, FPR1, KLF6, and NFKB1A, were significantly upregulated in Neu and Mono cells of the bone marrow of COVID-19 patients." (PMID 37087411, 2023). "Thus, FPR1 may be a novel therapeutic target for COVID-19-mediated inflammation and lung disease." (PMID 37248708, 2023).